ZNF548 (zinc finger protein 548)
Description:
May be involved in transcriptional regulation.
Synonyms: FLJ32932
Tractability: PROTAC: UniProt records ubiquitination sites on it; ubiquitination databases record sites on it.
Gene: Protein-coding gene on chromosome 19 (57,389,850 to 57,403,498, forward strand). Ensembl gene ENSG00000188785.
Subcellular location: Nucleus
Subcellular location (Human Protein Atlas): Nucleoplasm; Cytosol
Pathways (Reactome):
Gene expression (Transcription): Generic Transcription Pathway
Gene Ontology:
Molecular function: DNA-binding transcription factor activity, RNA polymerase II-specific; RNA polymerase II cis-regulatory region sequence-specific DNA binding
Biological process: regulation of transcription by RNA polymerase II; regulation of DNA-templated transcription
Cellular component: nucleus
Genetic constraint (gnomAD): Loss-of-function variants: 10 observed, 10.02 expected, observed/expected ratio (o/e) 1, 90% interval 0.61 to 1.65. The upper end of that interval is the gene's LOEUF score, 1.65, which puts it in group 6 of 6, group 1 being the genes least tolerant of losing a copy. Missense variants: 599 observed, 687.07 expected, observed/expected ratio (o/e) 0.87, 90% interval 0.81 to 0.93. Synonymous variants: 217 observed, 233.5 expected, observed/expected ratio (o/e) 0.93, 90% interval 0.83 to 1.04.
Homologues: Orthologues: chimpanzee ZNF548 (99% identical), rabbit ZNF548 (78% identical), dog ZNF548 (69% identical), mouse Zfy1 (20% identical), tropical clawed frog zfx (19% identical), rat Zfy1 (19% identical), mouse Zfy2 (19% identical), zebrafish zfx (18% identical). Paralogues in human: ZNF304 (51% identical), ZNF792 (50% identical), ZNF551 (49% identical), ZNF256 (49% identical), ZNF549 (47% identical), ZNF587B (44% identical), ZNF418 (43% identical), ZNF772 (42% identical), ZIK1 (41% identical), ZNF773 (38% identical), ZNF480 (38% identical), ZNF419 (38% identical), and 26 more.
Diseases named in the same sentence as ZNF548 in open-access papers:
ZNF548 is named in the same sentence as 1 disease in open-access papers, as found by Europe PMC text mining. Sharing a sentence is not in itself a finding about the gene and the disease. The quoted sentences say what the papers report.
cancer (1 paper, 2015). A tumor composed of atypical neoplastic, often pleomorphic cells that invade other tissues. "Despite the generally low PSI values for the 325 cryptic 3’SSs from the CLL-only analysis, we identified four genes previously implicated in cancer (TTI1, MAP3K7, FXYD5, PFDN5) and six others (YIF1A, ORAI2, ZNF91, ZNF548, RP11–1280I22." (PMID 25768983, 2015).